BDNF (brain derived neurotrophic factor)
Diseases named in the same sentence as BDNF in open-access papers (continued):
Sharing a sentence is not in itself a finding about the gene and the disease.
optic neuritis (1 paper, 2019). Optic neuritis is inflammation of the optic nerve, the nerve that carries the visual signal from the eye to the brain.The conditionmay cause sudden, reduced vision in the affected eye(s). "A total of 17 NMOSD subjects (34 eyes) were included in the study and were divided into subgroups based on optic neuritis (ON) history and BDNF Val66Met polymorphisms." (PMID 31803011, 2019).
oropharynx squamous cell carcinoma (1 paper, 2019). A squamous cell carcinoma that involves the oropharynx. "Taken together, HPV+ oropharynx squamous cell carcinoma, in agreement with available literature, has a preferred prognosis, partly based on effective apoptosis induction of therapeutic agents and inefficiency of survival factors such as BDNF." (PMID 30641914, 2019).
ovarian tumors (1 paper, 2025). "BDNF and the nerve marker neurofilament protein expression were examined in 108 human ovarian tumors." (PMID 40359002, 2025).
Paranoia (1 paper, 2018). The feeling and belief that one is being targeted or is a focus of negative or untoward actions, overt or covert, from others. "This study also included effects of the BDNF Val66Met polymorphism, showing that carriers of the BDNF 66Met allele presented more social stress-induced paranoia than individuals with the Val/Val genotype." (PMID 28822116, 2018).
paraplegia (1 paper, 2022). Complete paralysis of the lower half of the body including both legs, often caused by damage to the spinal cord. "The present study is the first to investigate the effect of acute submaximal exercise on BDNF using SCI guideline conditional recommendations in people with paraplegia and tetraplegia." (PMID 36451805, 2022). "Nonetheless, the discrepancy in relative intensity of exercise between people with paraplegia vs. tetraplegia did not differentially impact the BDNF response, albeit the current trial is underpowered to statistically compare BDNF responses between groups." (PMID 36451805, 2022).
peanut allergy (1 paper, 2021). "They determined several potential new genes associated with peanut allergy, such as BDNF (neurotrophin) and SERPINE1 (serine protease inhibitor), showing a new research line to elucidate the molecular basis of peanut allergy." (PMID 34959895, 2021).
Peri-Implantitis (1 paper, 2024). An inflammatory process with loss of supporting bone in the tissues surrounding functioning DENTAL IMPLANTS. "We speculated that a similar process may be needed to re-establish osseointegration disrupted by peri-implantitis and that BDNF may influence MSCs and osteoblasts to promote re-osseointegration." (PMID 39589662, 2024). "The present study aims to determine whether the brain-derived neurotrophic factor (BDNF)/high-molecular-weight hyaluronic acid (HMW-HA) complex could regenerate bone around implants lost due to peri-implantitis." (PMID 39589662, 2024). "The BDNF/HMW-HA complex appears to promote bone regeneration when combined with non-surgical debridement for peri-implantitis." (PMID 39589662, 2024). "Our results suggest that the BDNF/HMW-HA complex may promote bone regeneration when used along with non-surgical debridement to treat peri-implantitis." (PMID 39589662, 2024).
peripheral demyelinating neuropathy (1 paper, 2017). "Two recent studies have investigated the potential of using BDNF as a therapeutic strategy to treat peripheral demyelinating neuropathy." (PMID 28680965, 2017). "This study demonstrates that a BDNF-based peptide mimetic ameliorates the clinical and functional deficits in experimental autoimmune neuritis (EAN), an animal model of peripheral demyelinating neuropathy." (PMID 28680965, 2017). "Here, we investigated the therapeutic efficacy of a small structural mimetic of the region of BDNF that binds to p75NTR (cyclo-dPAKKR) in experimental autoimmune neuritis (EAN), an established animal model of peripheral demyelinating neuropathy." (PMID 28680965, 2017).
peripheral nerve lesion (1 paper, 2015). "During the repair phase following peripheral nerve lesion, dedifferentiated Schwann cells secrete a variety of neurotrophic factors and cytokines including NGF, BDNF, NT-4/5, FGF-2, IGF-1, IL-6, and IL-1ß that support neuronal survival and regenerative growth of axons." (PMID 26635533, 2015).
placental insufficiency (1 paper, 2022). Failure of the placenta to deliver an adequate supply of nutrients and oxygen to the fetus. "Despite the low number of samples, the reduced expression of NGF in the allantois and the reduced expression of BDNF in the amnion seems to characterize the fetal membranes of mares with placental insufficiency that delivered foals affected by NE." (PMID 36136675, 2022).
Pleural effusion (1 paper, 2018). The presence of an excessive amount of fluid in the pleural cavity. "We observed that high BDNF expression, at the mRNA level in tumors or at the protein level in pleural effusions (PE), was a specific hallmark of MPM samples." (PMID 30309369, 2018).
postmenopausal osteoporosis (1 paper, 2022). Metabolic disorder associated with fractures of the femoral neck, vertebrae, and distal forearm. "BDNF/TrkB signaling activates Akt that phosphorylates and inhibits asparagine endopeptidase (AEP), which regulates the differentiation fate of human bone marrow stromal cells (hBMSC) and is altered in postmenopausal osteoporosis." (PMID 35973996, 2022).
premature ovarian failure (1 paper, 2022). "Recently, Ab4B19, a TrkB agonist antibody, was developed to treat premature ovarian failure associated with dysfunction of BDNF/TrkB signaling." (PMID 35898394, 2022).
pulmonary embolism (1 paper, 2022). The obstruction of the pulmonary artery or one of its branches by an embolus, sometimes associated with infarction of the lung. "Furthermore, we performed a binary logistic regression to analyze the combination between BDNF levels and D-dimer levels for the diagnosis of pulmonary embolism." (PMID 36078878, 2022).
pulmonary sarcoidosis (1 paper, 2010). Sarcoidosis affecting the lung parenchyma. "This indicates that besides NGF and NT-3, BDNF could be a messenger molecule of relevance in pulmonary sarcoidosis." (PMID 21059230, 2010). "The aim of the present study was to compare the concentrations of the neurotrophins NGF, BDNF and NT-3 in BALF of patients with newly diagnosed pulmonary sarcoidosis with those of healthy controls." (PMID 21059230, 2010). "The concentrations of NGF, BDNF and NT-3 in bronchoalveolar lavage fluid (BALF) of 41 patients with newly diagnosed pulmonary sarcoidosis and 27 healthy controls were determined with ELISA." (PMID 21059230, 2010).
reactive depression (1 paper, 2022). "There was a negative correlation between the HAMD-24 scores and the expression levels of BDNF in the reactive depression group (r = −0.436, P = 0.013)." (PMID 35295780, 2022). "Our findings suggested the serum NLRP3 and BDNF levels could be potential biomarkers for detecting and evaluating the severity of reactive depression." (PMID 35295780, 2022). "Hence, the serum NLRP3 and BDNF levels could be potential biomarkers for detecting and evaluating the severity of reactive depression." (PMID 35295780, 2022). "There was a significant negative correlation between the serum BDNF level of reactive depression and the HAMD-24 total scores." (PMID 35295780, 2022). "There was a significant negative correlation between the BDNF level and the HAMD-24 total scores for patients with reactive depression." (PMID 35295780, 2022).
reading disorder (1 paper, 2023). A learning disability involving difficulty reading resulting primarily from neurological factors which affect any part of the reading process. "It is difficult to judge whether the change in the BDNF level (reduction when compared to NT children) is a cause or a result of the reading disorder and the altered light signal processing, which could be considered a limitation of the study." (PMID 37786524, 2023).
refractive error (1 paper, 2025). A defect in the focusing of light on the retina as in astigmatism, myopia, or hyperopia. "Since not all high-myopic eyes develop mCNV, implying the existence of some neuroprotective mechanisms, we hypothesized the participation of NGF and BDNF as well as few oxidative-related and epigenetic factors in the progression of this refractive error." (PMID 40650128, 2025).
renal adenocarcinoma (1 paper, 2023). "Here, we demonstrated that Shiikuwasha extracts increased the BDNF level in human renal adenocarcinoma ACHN." (PMID 38082356, 2023). "In our previous study, we demonstrated that the human renal adenocarcinoma cell line ACHN produces and secretes BDNF." (PMID 38082356, 2023). "Previously, we demonstrated that Citrus unshiu peel (Chinpi) and C. natsudaidai increased BDNF level in a human renal adenocarcinoma cell line ACHN, which has BDNF-producing ability." (PMID 38082356, 2023).
retinal (1 paper, 2020). "Dysregulation of these miRNAs correlated with increased Vascular Endothelial Growth Factor (VEGF) and decreased Brain-Derived Neurotrophic Factor (BDNF) levels in diabetic retinas, before appearance of retinal microaneurysms." (PMID 32210819, 2020).
schwannoma (1 paper, 2021). A benign, usually encapsulated slow growing tumor composed of Schwann cells. "Our study validated this work by determining the transfection efficiency of cationic liposomes encapsulating BDNF AT in RT4-D6P2T rat schwannoma cells as compared to only BDNF AT in saline." (PMID 33953687, 2021). "The in vitro data confirmed that our BDNF AntagoNAT constructs encapsulated in liposomes are capable of inducing both BDNF transcription and translation in BDNF NAT-expressing rat schwannoma cells at 48 h." (PMID 33953687, 2021). "Uptake, distribution and transfection efficiency of BDNF AntagoNAT’s in saline and liposomes were evaluated qualitatively (microscopy) and quantitatively (ELISA and AT hybridization assays) in RT4-D6P2T rat schwannoma cells and in naïve rats." (PMID 33953687, 2021).
scrapie (1 paper, 2020). A fatal disease of the nervous system in sheep and goats, characterized by pruritus, debility, and locomotor incoordination. "Interestingly, in the brain tissue of scrapie infected rodents, BDNF, TrkB, phospho-TrkB, GRB2 and p75NTR were all significantly down-regulated supporting the direct association identified in our results between GRB2 and p75NTR31,32." (PMID 32917932, 2020).
septic shock (1 paper, 2017). Shock caused by infection; frequently caused by gram negative bacteria, although some cases have been caused by other bacteria, viruses, fungi, and protozoa; characterized by fever, chills, tachycardia, tachypnea, and hypotension. "In myocardium from CLP-induced septic shock rats, cardiac BDNF level was significantly reduced accompanied with increased cardiomyocyte apoptosis and enhanced oxidative stress, which were associated with cardiac dysfunction and increased mortality rate." (PMID 28770018, 2017).
serous carcinomas (1 paper, 2020). "Our data suggest that BDNF in the ovarian FF protects FTE tumor precursors and may contribute to the progression from FT lesions into widespread high-grade serous carcinomas." (PMID 32471985, 2020).
Skin ulcer (1 paper, 2024). A discontinuity of the skin exhibiting complete loss of the epidermis and often portions of the dermis and even subcutaneous fat. "No skin ulcer nor abnormal histological structure, such as immune cell infiltration, was found in the skin of MBKO mice, suggesting BDNF deficiency in muscle did not induce the typical cutaneous manifestations of DM." (PMID 39531828, 2024).
small-fiber neuropathy (1 paper, 2024). "The positive staining of PGP9.5 showed that PRF caused small-fiber neuropathy, and such small-diameter “pain” fiber activation was related to the elevation in spinal BDNF levels." (PMID 39000303, 2024).
speech disorder (1 paper, 2021). A term referring to disorders characterized by the disruption of normal speech. "There was also a relationship between high plasma BDNF levels and a higher intensity of ocular motor disorders, both in horizontal and vertical pursuits (p = 0.01, R = 0.94), speed of horizontal saccades (p = 0.01, R = 0.94), and severity of speech disorders (p = 0.04, R = 0.89)." (PMID 34768699, 2021).
spinal cord disease (1 paper, 2023). "The therapeutic effect of OPC transplantation on white matter injury in spinal cord disease has been attributed in part to secreted growth factors, such as BDNF." (PMID 37821228, 2023).
spinal cord ischemia (1 paper, 2014). Reduced blood flow to the spinal cord which is supplied by the anterior spinal artery and the paired posterior spinal arteries. "ASCs have neuroprotective effects against spinal cord ischemia and these effects persisted up to 3 weeks after ischemia/reperfusion by reducing the microglial activation and increasing BDNF levels." (PMID 24592394, 2014).
squamous cell carcinoma (1 paper, 2017). A carcinoma arising from squamous epithelial cells. "Further, CAF-derived BDNF contributes mechanistically to the development of a pro-invasive and pro-angiogenic metastatic milieu that promotes aggressive tumor behavior and adverse outcomes among patients with squamous cell carcinoma." (PMID 28966935, 2017).
syphilis (1 paper, 2019). A contagious bacterial infection caused by the spirochete Treponema pallidum. "Finally, our analysis indicated there might be differences in cytokine concentration responses, particularly Resistin, BDNF, CD40L, and IFNB, during incident syphilis versus cured syphilis." (PMID 31186010, 2019).
systemic amyloidosis (1 paper, 2020). "B2M is responsible for systemic amyloidosis, which can dysregulate the levels of BDNF and NGF." (PMID 32059688, 2020).
tongue tumor (1 paper, 2023). "It was shown that locally blocking BDNF reversed tongue tumor-induced pain behaviors in vivo and that peripheral TrkB receptors had a key role in this condition." (PMID 37569811, 2023).
uterine fibroid (1 paper, 2022). "We have highlighted the differential expression of 3 genes (BDNF, CCND1, and VWF) in our results that we think could play key roles in uterine fibroid etiology or pathogenesis." (PMID 36066972, 2022).
uterine leiomyosarcoma (1 paper, 2012). "Moreover, we demonstrated the expression level of TrkB and BDNF in uterine leiomyosarcoma associated with clinical malignancy in patients." (PMID 22911740, 2012). "Future studies of galectin-1 in uterine leiomyosarcoma would provide a better understanding of BDNF-TrkB signaling mediated-cell growth." (PMID 22911740, 2012). "In our leiomyosarcoma cases, clinical stage of the group with high-BDNF/TrkB was stage I (n = 1) and stage IV (n = 2), whereas low-BDNF/TrkB group was stage I (n = 2) and stage IV (n = 2)." (PMID 22911740, 2012). "Together, these results prompted us to investigate the endogenous roles of BDNF/TrkB signaling in the malignant uterine smooth muscle tumor, leiomyosarcoma." (PMID 22911740, 2012). "In uterine leiomyosarcoma group, three patients with high TrkB transcript levels also showed increased BDNF expressions (closed circles)." (PMID 22911740, 2012). "Further elucidation of the mechanisms of BDNF/TrkB-induced leiomyosarcoma growth could lead to novel therapeutic approaches for the treatment of patients with this disease." (PMID 22911740, 2012). "Although SKN is derived from a uterine leiomyosarcoma distinct from that which gave rise to the MES-SA and MES-SA/Dx5 cells, its proliferation was also suppressed by inhibiting TrkB signaling, suggesting important endogenous roles of BDNF/TrkB signaling in growth of leiomyosarcoma cells." (PMID 22911740, 2012). "Interestingly, the leiomyosarcoma patients with high BDNF expression also showed significantly high levels of TrkB, but not NT4/5." (PMID 22911740, 2012). "In leiomyosarcoma cell line, SKN, expression of TrkB, p75NTR, BDNF and NT4/5 were detected, too." (PMID 22911740, 2012).
uterine sarcoma (1 paper, 2012). "We demonstrated the ability of endogenous BDNF to promote the proliferation and survival of uterine sarcoma cells using the TrkB ectodomain and the Trk inhibitor, K252a." (PMID 22911740, 2012). "Although NT4/5 is another TrkB ligand, its expression levels in uterine sarcoma cells are low, suggesting that BDNF acts as the predominant ligand in the context of uterine sarcoma cell growth." (PMID 22911740, 2012). "The suppressive effect of K252a on MES-SA/Dx5 tumor growth in athymic nude mice indicated that BDNF/TrkB signaling also played a significant role in uterine sarcoma growth and protection against apoptosis in vivo." (PMID 22911740, 2012). "The expression of TrkB, BDNF and NT4/5 in uterine sarcoma cells was confirmed at the protein level using immunofluorescent staining (MES-SA/Dx5 cells)." (PMID 22911740, 2012). "In this study, we found that both BDNF and TrkB mRNA levels were increased in the multidrug-resistant (MES-SA/Dx5), as compared to the drug sensitive (MES-SA), uterine sarcoma cell line." (PMID 22911740, 2012).
vasculitis (1 paper, 2023). "Furthermore, proBDNF, and BDNF, as well as its receptor, may serve as inflammatory biomarkers in vasculitis." (PMID 37143663, 2023).
Visual impairment (1 paper, 2025). "BDNF levels were significantly higher in older individuals with normal vision compared to those with visual impairment [4.28 (0.98, 11.84) μg/L vs. 1.61 (0.36, 6.19) μg/L, Z = −4.845, P < 0.001]." (PMID 40513379, 2025). "We also found that BDNF levels in older individuals with visual impairment were significantly lower than those in visually normal individuals." (PMID 40513379, 2025).
ZIKV infection (1 paper, 2020). "BDNF, which is important in the development of the brain, was found in the placenta, and could be a promising marker to predicting the impact of a maternal ZIKV infection on fetal brain alterations if considered together with others." (PMID 32983175, 2020).